BRD4 (bromodomain containing 4)
Diseases named in the same sentence as BRD4 in open-access papers (continued):
Sharing a sentence is not in itself a finding about the gene and the disease.
liver fibrosis (25 papers, 2016 to 2026). "Recent studies have increasingly implicated BRD4 in the regulation of non-alcoholic steatohepatitis, liver fibrosis, and inflammation, thereby reinforcing its potential role in immune responses to S. japonicum infection." (PMID 40616163, 2025). "Bromodomain-containing protein 4 (BRD4) has been implicated to play a regulatory role in fibrogenic gene expression in animal models of liver fibrosis." (PMID 34336890, 2021). "The primary target of LIVTAC in the treatment of liver fibrosis is BRD4, a bromodomain-containing protein known to regulate fibrotic gene expression in HSCs." (PMID 40756370, 2025). "Studies have shown that BET inhibitors, such as JQ1, can disrupt BRD4-Med1 condensates, demonstrating potential therapeutic effects in the treatment of liver fibrosis and HCC." (PMID 41280670, 2025). "In conclusion, this study introduces LIVTAC XZ1606 as a novel and selective therapeutic agent capable of reversing hepatic fibrosis and steatosis through targeted degradation of BRD4." (PMID 40756370, 2025). "This mechanistic insight supports the potential of XZ1606 as a selective therapeutic agent for liver diseases, such as liver fibrosis, where BRD4 plays a crucial role." (PMID 40756370, 2025). "In summary, BRD4 can serve as an effective target for treating hepatic fibrosis, and BRD4 inhibition can significantly attenuate the progression of hepatic fibrosis through TGF-β, inflammation and other signaling pathways." (PMID 39215370, 2024). "Second, similar to its role in pulmonary fibrosis, BRD4 synergistically promotes with the TGF-β signaling pathway in hepatic fibrosis." (PMID 39215370, 2024). "Taken together, these findings suggest that BRD4 can serve as an effective target against hepatic fibrosis." (PMID 39215370, 2024). "Research has demonstrated that BRD4 has the capacity to facilitate the progression of liver fibrosis via various pathways." (PMID 39215370, 2024). "TGF-β1 further facilitates the binding of Egr1 to the BRD4 promoter, thereby promoting the expression of BRD4, leading to HSCs activation and hepatic fibrosis." (PMID 39215370, 2024). "Increased CCL2 expression with the involvement of the epigenetic reader BRD4 leads to hepatic fibrosis and portal hypertension." (PMID 39215370, 2024). "The expression of BRD4 is positively correlated with the severity of hepatic fibrosis as well as alanine transaminase (ALT) and aspartate transaminase (AST) levels in HBV-induced hepatic fibrosis." (PMID 39215370, 2024). "Components of an SE complex, such as BRD4, C/EBPα, CDK7 and MED1, have been subjected to in-depth research and found to be associated with liver fibrosis." (PMID 36726725, 2023). "Serving as a coactivator for gene transcription, BRD4 has been found to be related to liver fibrosis, HCC and hepatitis B virus infection." (PMID 36726725, 2023). "Our data indicate that BRD4 play a critical role in the progress of liver fibrosis, and it holds promise as a potential target for intervention of liver fibrosis." (PMID 34336890, 2021). "Intrigued by the previous findings, we performed the first study to characterize the expression of BRD4 in patients with liver fibrosis." (PMID 34336890, 2021). "BRD4 protein expression was increased in the samples from all enrolled patients with liver fibrosis/cirrhosis compared with the expression in the control samples." (PMID 34336890, 2021). "RNA-seq showed that hepatic BRD4 mRNA was elevated in patients with liver fibrosis compared with that in healthy controls." (PMID 34336890, 2021). "BRD4 expression was positively correlated with the severity of liver fibrosis, and also correlated with the serum levels of aspartate aminotransferase and total bilirubin." (PMID 34336890, 2021). "It was recently reported that hepatic CXCL6 expression is up-regulated in liver fibrosis and can promote the interaction of BRD4 with other transcriptional factors." (PMID 34336890, 2021).
liver fibrosis (continued). "Nevertheless, the roles of BRD4 in hepatocytes, macrophages, and biliary tract cells during liver fibrosis remain to be further studied." (PMID 34336890, 2021). "Our findings through conducting this study indicate that BRD4 plays important roles in the development and progression of liver fibrosis in humans." (PMID 34336890, 2021). "Given that HBV-induced liver fibrosis is the most common type of liver fibrosis in China due to the high prevalence of HBV infection, we further analyzed the association of the BRD4 expression level with fibrosis severity and other parameters." (PMID 34336890, 2021). "Further in-depth investigations are underway in our laboratory to better understand the role of BRD4 in patients with liver fibrosis." (PMID 34336890, 2021). "BRD4 protein levels were significantly increased in HBV-, AIH-, PBC-, cholestasis-, and overlap syndrome-associated liver fibrosis/cirrhosis tissues." (PMID 34336890, 2021). "The BRD4 mRNA level was positively correlated with the CXCL6 mRNA level in the hepatic tissues of patients with liver fibrosis." (PMID 34336890, 2021). "Brd4 was recently identified as a critical regulator of lung and liver fibrosis and blocking Brd4 not only prevents but also reverses fibrosis and myofibroblast differentiation of hepatic stellate cells." (PMID 28534817, 2017). "Of particular note, BRD4 promotes the expression of Col1A1, which encodes Type I collagen, in response to exogenous TGF-β, thereby leading to both lung and liver fibrosis." (PMID 27990121, 2016). "Ultimately, mechanotransduction- and growth factor-induced gene regulation by transcriptional regulators such as YAP and BRD4 mediate fibroproliferative disease and represents a unique target for pharmacological intervention for patients with liver fibrosis." (PMID 27990121, 2016). "In conclusion, PML/BRD4-mediated SE activation via phase separation drives proinflammatory angiocrine signaling in LSECs, initiating the inflammatory cascade and subsequent immune cell recruitment during liver fibrosis." (PMID 41842990, 2026). "Thereby, PML/BRD4 in LSECs governs inflammatory immune cell recruitment in liver fibrosis." (PMID 41842990, 2026). "Although BRD4’s role in hepatic fibrosis progression and its effects on S. japonicum have been explored, whether it contributes to host resistance to S. japonicum, and its potential role in mediating immune response to S. japonicum, remains poorly understood." (PMID 40616163, 2025). "Notably, BRD4 has been implicated in HSCs activation via the JAK2/STAT3 signaling pathway, a crucial driver of liver fibrosis." (PMID 40616163, 2025). "We hypothesized that targeted degradation of BRD4 via XZ1606 would not only attenuate the fibrotic response in vitro but also ameliorate hepatic fibrosis and steatosis in vivo." (PMID 40756370, 2025). "Knockdown of BRD4 blocks the induction of HSCs activation and hepatic fibrosis via STAT3 signaling." (PMID 39215370, 2024). "However, recent studies have shown that BRD4 expression is enhanced in liver fibrosis, and BETs inhibition has an anti-fibrotic effect in both the liver and other organs." (PMID 36015180, 2022). "Moreover, in HBV liver fibrosis, BRD4 protein expression was correlated with the severity of liver fibrosis." (PMID 34336890, 2021). "Interestingly, the CXCL6 mRNA level was positively correlated to the BRD4 mRNA level in the liver fibrosis group." (PMID 34336890, 2021). "Subsequent multiple manipulations such as western blotting, real-time quantitative polymerase chain reaction, and dual immunofluorescence analysis confirmed the abnormal elevation of the BRD4 expression in liver fibrosis of various etiologies compared to healthy controls." (PMID 34336890, 2021). "LSEC-specific p300 deletion or BRD4 inhibitor could significantly attenuate macrophage infiltration and liver fibrosis." (PMID 34887768, 2021).
liver fibrosis (continued). "In summary, this study has demonstrated, for the first time to our knowledge, that hepatic BRD4 expression is markedly increased in patients with liver fibrosis with various etiological factors, and that elevated levels of BRD4 are associated with higher degrees of liver fibrosis." (PMID 34336890, 2021). "Moreover, the expression of C-X-C motif chemokine ligand 6 (CXCL6), a factor interplayed with BRD4, was increased in hepatic tissues of the patients with liver fibrosis." (PMID 34336890, 2021). "In view of the role of BRD4 in cell proliferation and apoptosis, BRD4 might be involved in the regeneration of hepatocytes in HBV-induced liver fibrosis." (PMID 34336890, 2021). "Such interactions between CXCL6 and BRD4 might promote the development and progression of liver fibrosis." (PMID 34336890, 2021). "Inhibition of BRD4 was also shown to protect against inflammation and liver fibrosis." (PMID 33290278, 2020). "In addition, miR-29a has been identified as a key regulon of BRD4 regulation and liver fibrosis decrease in mice by inhibiting hepatic stellate cell activation." (PMID 31694982, 2019). "Interestingly, a very recent study reported critical roles of BRD4 in liver fibrosis, demonstrating that JQ1 suppressed the activation of hepatic stellate cells and inhibited CCl4-induced liver fibrosis." (PMID 27528027, 2016). "In addition to JQ1, other BRD4 inhibitors have been used to treat hepatic fibrosis." (PMID 39215370, 2024). "Thus, BRD4 inhibitor JQ1 could attenuate liver fibrosis in a carbon tetrachloride (CCl4)-induced fibrotic murine model." (PMID 34887768, 2021). "The potential role of BRD4 in liver fibrosis in humans remains unclear." (PMID 34336890, 2021). "Notably, the BRD4 gene was increased in the liver fibrosis group vs. the normal control group." (PMID 34336890, 2021). "Although BRD4 has been implicated in the development and progression of experimental liver fibrosis in cell culture systems and animal models, its expression and function in liver fibrosis in humans has not been elucidated." (PMID 34336890, 2021). "By specifically targeting BRD4, XZ1606 aims to mitigate the aberrant activation of HSCs and interrupt the progression of liver fibrosis." (PMID 40756370, 2025). "During liver fibrosis, mediator complex subunit MED1 and epigenetic regulator BRD4 exhibit prominent LLPS activity, regulating the expression of fibrotic genes and ECM production." (PMID 41280670, 2025). "Our results showed that BRD4 protein expression was positively correlated with AST and TBIL in HBV-induced liver fibrosis." (PMID 34336890, 2021). "Given that BRD4 is a co-activator of NF-κB and promotes the transcription of chemokines and cytokines in various cells besides macrophages, there is a possibility that BRD4 may promote the initiation, development, and progression of liver fibrosis through certain inflammatory mediators." (PMID 34336890, 2021). "Thus, our data suggest that the up-regulation of BRD4 may be associated with a common pathway for liver fibrosis, rather than the cause of liver fibrosis." (PMID 34336890, 2021). "BRD4 and YAP both regulate profibrotic gene expression that plays a central role in HSC activation, tissue remodeling and liver fibrosis." (PMID 27990121, 2016). "In the context of fibrosis, inhibiting BRD4 with JQ1 inhibits both lung and liver fibrosis as well as HSC activation in murine models, including reducing TGF-β-mediated Col1A1 expression and extracellular matrix remodeling." (PMID 27990121, 2016). "Knockdown of BRD4 in HSCs attenuated their activation and ECM production, and treatment of fibrotic mice with a BRD4 inhibitor (the BET bromodomain inhibitor JQ1) significantly reduced liver fibrosis." (PMID 40149956, 2025). "Macrophages have recently been shown to play a critical role in liver fibrosis in NASH, suggesting that the up-regulation of BRD4 in macrophages might be involved in the progression of liver fibrosis." (PMID 34336890, 2021).
liver fibrosis (continued). "BRD4 is up-regulated in liver fibrosis, regardless of etiology, and its increased expression is positively correlated with higher degrees of liver fibrosis." (PMID 34336890, 2021). "It was reported that bromodomain-containing protein 4 (BRD4) was critical in activation of HSCs, while experiments in murine models showed inhibitor of BRD4 could attenuate liver fibrosis and tumorigenesis through repressing TGF-β signaling pathway." (PMID 33292618, 2020). "Furthermore, we recently uncovered that anti-fibrotic effect of miR-29a is associated with inhibition of bromodomain-containing protein 4 (BRD4) in HSC, which represents a novel therapeutic target of liver fibrosis." (PMID 32331364, 2020). "Moreover, BRD4 could promote PLK1 expression through P300/H3K27ce, thereby enhancing hepatic stellate cells activation and hepatic fibrosis." (PMID 37980502, 2023). "Furthermore, Western blot analysis of liver tissues revealed elevated expression of BRD4, but not BRD2 and BRD3 in the CDAA-HFD group, again suggesting BRD4 as the major protein that mediates liver fibrosis." (PMID 40756370, 2025).
Burkitt lymphoma (19 papers, 2015 to 2024). A rare form of malignant mature B-cell non-Hodgkin lymphoma. "The administration of ARV-825 resulted in total BRD4 degradation in cells of Burkitt's lymphoma (BL) (DC50 < 1 nM)." (PMID 38389844, 2024). "For example, in Burkitt’s lymphoma cells, high concentrations and continuous exposure to BRD4 inhibitors were required to suppress the expression of c-MYC." (PMID 36733715, 2023). "Through the recruitment of BRD4 to the E3 ubiquitin ligase cereblon, ARV-825 (a BRD4 degrader) can induce efficient and sustained degradation of BRD4 in Burkitt’s lymphoma cell lines." (PMID 37005672, 2023). "While the cis-isomer is inactive, the trans-isomer with the desired stereochemistry is active in BRD4 degradation in Burkitt lymphoma Ramos cells." (PMID 32404196, 2020). "BRD4 belongs to BET family member and preclinical studies with BRD4 inhibitors demonstrate the suppression of MYC expression in MYC-driven Burkitt’s lymphoma cell lines." (PMID 36465385, 2022). "ARV-825, consisting of pomalidomide and BRD4 inhibitor OTX015, induced degradation of BRD4 and inhibited proliferation of Burkitt lymphoma cells at sub-nanomolar levels." (PMID 32404196, 2020). "In addition, the research group also designed a BRD4-targeting compound PROTAC 28 in 2015, which demonstrated rapid, efficient, and prolonged BRD4 degradation in all tested Burkitt’s lymphoma (BL) cell lines." (PMID 36142231, 2022). "In Burkitt’s lymphoma (BL) cell lines, the PROTAC ARV-825 consists of OTX015 and pomalidomide has an apoptosis-inducing and antiproliferative function, which provide a better strategy for efficiently targeting BRD4." (PMID 31311566, 2019). "Similarly, the improved pharmacodynamics could be replicated by another BRD4-targeting PROTAC, ARV-825, in Burkitt’s lymphoma cell lines showing promising results for MYC-driven malignancies." (PMID 33324551, 2020).
medulloblastoma (19 papers, 2013 to 2025). A malignant, invasive embryonal neoplasm arising from the cerebellum. "Although the BRD4 level did not stratify patient survival in the total medulloblastoma cohort, a lower BRD4 expression level was associated with significantly better survival in the SHH medulloblastoma subgroup." (PMID 36688010, 2022). "Because c-MYC is a key driver of high risk medulloblastoma we first asked whether BRD4 inhibition by JQ1 would alter c-MYC driven signaling in medulloblastoma cells." (PMID 24796395, 2014). "However, cerebellum-associated developmental disorders and pediatric cerebellar tumors such as medulloblastoma are associated with deficits in procedural learning, which could be exacerbated with prolonged Brd4 inhibitor usage." (PMID 31292434, 2019). "A third case was found in a series of medulloblastoma, where re-evaluation using version 12 of the Heidelberg classifier showed a match to CNS embryonal tumor with BRD4::LEUTX fusion." (PMID 38500181, 2024). "Treatment with the orally bioavailable BRD4 inhibitor MK-8628 suppresses medulloblastoma cell proliferation and induces apoptosis by reducing MYC expression, and MK-8628 suppresses medulloblastoma tumor progression in preclinical models." (PMID 38135679, 2023). "A reverse combination drug screen identifies CDK4/CDK6 inhibitors as the compounds exerting the best synergy with the BRD4 inhibitor JQ1 against medulloblastoma cells." (PMID 38135679, 2023). "Another combination therapy using CDK2 inhibitors with bromodomain-containing protein 4 (BRD4) inhibitors in MYC amplified medulloblastoma resulted in MYC suppression and promoted apoptosis." (PMID 33805800, 2021). "Brd4 controls expression of the medulloblastoma essential gene MYC in G3 medulloblastomas, which have poor prognosis as well as GLI1 and GLI2 levels in Sonic hedgehog (SHH)-driven medulloblastomas, which have intermediate prognosis." (PMID 31292434, 2019). "Our work indicates that BRD4 inhibition attenuates stem cell signaling in MYC driven medulloblastoma and demonstrates the feasibility BET domain inhibition as a therapeutic approach in vivo." (PMID 24796395, 2014). "Excitingly, while this work was in preparation two other reports demonstrated that BRD4 inhibition with JQ1 can inhibit medulloblastoma cell growth in vitro and in vivo." (PMID 24796395, 2014). "Here we report that MYC driven medulloblastoma can be targeted by inhibition of the bromodomain protein BRD4." (PMID 24796395, 2014). "Together these findings indicate that BRD4 prevents differentiation of medulloblastoma cells by enforcing a stem cell transcriptional program and promoting tumor cell self-renewal." (PMID 24796395, 2014). "To characterize the phenotypic consequences of BRD4 inhibition on medulloblastoma cells we first determined the impact of JQ1 treatment on medulloblastoma cell growth." (PMID 24796395, 2014). "Here we show that the BET domain protein BRD4 is a mediator of medulloblastoma growth in the context of MYC pathway activation." (PMID 24796395, 2014). "There was a significant decrease in the ability of medulloblastoma cells to form colonies in BRD4 depleted cells." (PMID 24796395, 2014). "Here we show that BRD4 inhibition is a highly effective strategy to inhibit MYC driven medulloblastoma." (PMID 24796395, 2014). "In the context of decreased expression of stem cell markers we found that JQ1 mediated BRD4 inhibition drives senescence in medulloblastoma cells with a significant up regulation of cell cycle kinase inhibitors." (PMID 24796395, 2014). "Together these data suggest that BRD4 inhibition can be a highly effective strategy to target tumor stem cells in medulloblastoma and other MYC driven tumors." (PMID 24796395, 2014). "Excitingly JQ1 was effective in depleting SOX2 positive tumor cells in vivo and in decreasing SOX2 mRNA expression further confirming that BRD4 inhibition suppresses the tumor stem cell phenotype in medulloblastoma." (PMID 24796395, 2014).